CCND1 (cyclin D1)
Diseases named in the same sentence as CCND1 in open-access papers (continued):
Sharing a sentence is not in itself a finding about the gene and the disease.
tumor (continued). "Molecular analysis revealed that the tumor-suppressive effect of CHL1 regulates cell cycle arrest at G1/S checkpoint by down-regulating cyclin D1, which is accumulating before S-phase and reaching its maximum." (PMID 31523184, 2019). "CCND1 gene expression was highest in luminal A/B and lowest in basal-like tumours, while the opposite was true for CDK4/6 and the proliferation marker gene MKI67." (PMID 30819233, 2019). "ROC curve was used to analyze the ability of CCND1 and tumor grade to discriminate between ccRCC patients with or without recurrence." (PMID 31183974, 2019). "When we considered the statuses of both genes, the synergistic effects of EGFR and CCND1 were associated with tumor stage (p < 0.01), LNM (p < 0.01), and tumor differentiation (p < 0.01)." (PMID 31159251, 2019). "Previously, it was reported that tumor mechanisms of primary resistance include mutations in RAC1, loss of PTEN, and copy number increase of CCND1, while secondary resistance mechanisms include alternative expression of BRAF and PI3K." (PMID 30885146, 2019). "In general, CCND1-amplified tumours were more likely to be ER-positive and of luminal subtype relative to non-amplified tumours." (PMID 30819233, 2019). "The AUC of combined CCND1 and tumor grade was 0.734, suggesting CCND1 can help distinguish potential recrudescent patients." (PMID 31183974, 2019). "As a key element of the initiation translation complex, eIF4E participates in the translation of tumor–associated proteins, such as c‐MYC, cyclin D1, and MCL‐1 (Kosciuczuk, Saleiro, & Platanias, 2017)." (PMID 30891950, 2019). "Here, we demonstrated that YC-1 suppresses tumor cell proliferation through reducing the expression of Wnt target genes such as cyclin D1." (PMID 31086087, 2019). "Consistently, we also found that the percentages of β-catenin-, PCNA- and cyclin D1-positive cells in the tumor tissues of Ct55 knockout mice were lower than those in the WT mice after AOM/DSS treatment." (PMID 30944312, 2019). "The tumor-suppressive activity of miR-625 upregulation on ccRCC cells was reversed by CCND1 reintroduction." (PMID 31434797, 2019). "Like Cyclin-D1, tumor cells in both the control as well as the Rapamycin-treated groups were positive for PCNA." (PMID 30863496, 2019). "When combining both cohorts, worse survival was found for patients with CCND1-amplified tumours in luminal A (HR = 1.68; 95% CI, 1.15–2.46), luminal B (1.37; 1.01–1.86) and ER+/LN−/HER2− (1.66; 1.14–2.41) subgroups." (PMID 30819233, 2019). "It has also been reported that miR-326/330-5p clusters can target cyclin D1 gene, CCND1, exerting their tumor-suppressive roles on NPC initiation." (PMID 31456943, 2019). "We also found a strong increase of cyclin D1 in temsirolimus resistant tumor cells accompanied by a considerable reduction of p73." (PMID 31167517, 2019). "Phosphorylation of β-catenin at S33 and S37 promotes its degradation, and its downstream target genes c-myc and cyclin D1 are responsible for tumor proliferation or malignant progression." (PMID 31355268, 2019). "Similar trends were found for CCND1-amplified tumours in Kaplan–Meier and multivariable analyses of a second independent cohort of 340 patients; however, smaller patient numbers resulted in wider confidence intervals and reduced statistical power." (PMID 30819233, 2019). "At the end, the relationship between the expression of cyclin D1 and various variables including tumor grades, tumor subtypes and patient demographic features were examined using appropriate statistical tests." (PMID 31583003, 2019). "On the other hand, dysregulation of cyclin D1 is a marker of senescence, which counteracts tumor genesis." (PMID 30665445, 2019).
tumor (continued). "Regarding the other RNAs analysed, they revealed to be upregulated in most of the tumours, namely CCND1 (52%), PKM2 (67%) and PTBP1 (46%)." (PMID 31461477, 2019). "Various studies confirmed this pro-proliferative and tumor initiating effect in vitro and in vivo and identified several downstream mechanisms e.g. cyclin D1 and Rb or p21 and p27." (PMID 31752925, 2019). "In xenografted mouse model, we measured the tumor size before and after the Adv-mfn2 or Adv-control treatment, and analyzed the expression of Cyclin D1, Ras, Myc, ERK1/2, NF-κB p65, mTOR proteins by western blot." (PMID 31384172, 2019). "According to our observation, overexpression of Wnt3 in CRC cell line accelerated the cellular proliferation and tumor growth in nude mice, through activating the β-catenin-dependent target oncogenes like c-Myc and cyclin D1 in Wnt signaling." (PMID 31632267, 2019). "We analyzed the expression of Cyclin D1 and Survivin, which are involved in tumor proliferation and are downstream molecules of STAT3 signaling." (PMID 30832202, 2019). "For example, ZNF322A and c-Jun cooperatively bind to AP-1 elements on the cyclin D1 and alpha-adducin promoters to transcriptionally upregulate their expression to enhance tumor growth and tumor metastasis." (PMID 30258097, 2019). "And co‐transfection of CCND1 abrogated the tumour suppressive role of miR‐551b‐3p overexpression in CCA cells." (PMID 31199052, 2019). "As an oncogene, high level of CCND1 was observed and related to poor prognosis and tumor recurrence in many cancers." (PMID 31183974, 2019). "This patient’s tumor cells also carried an amplification in each CTC of the 11q13.3 locus containing Cyclin D1 gene (CCND1), as well as gains of NOTCH3 (19p13.2), HTERT (5p15.33), and PDPK1 (16p13.3)." (PMID 31481116, 2019). "In summary, Fx significantly suppressed the tumor incidence (development) and Cyclin D1 expression in the xenograft mice along with increasing a tumor metabolite predictor, glycine." (PMID 30705512, 2019). "miR-302a has also been reported to reduce cell proliferation and tumor formation by downregulating cyclin D1 (CCND1) and AKT1." (PMID 31001342, 2019). "The top-scoring PCA component in the random forest prediction is strongly influenced by the cell cycle gene CCND1, overexpression of which correlates with early cancer onset and tumor progression." (PMID 30742607, 2019). "IHC staining was performed to evaluate the protein level of DACH1, CXCL1, cyclin D1, and Ki67 in nude mice xenograft tumor tissues from cells expressing vector control and DACH1." (PMID 31998654, 2019). "Meanwhile, using the median expression as the cutoff point, we tested the probability of tumor recurrence in the CCND1 low and high expression groups." (PMID 31183974, 2019). "Here, we observed immune responses to various antigens, among these established tumor-antigens such as cyclin D1 used already in different vaccination approaches, but also in one case the recognition of a predicted mutation-derived peptide." (PMID 31803175, 2019). "Tumor RNA isolation showed significantly decreased steady-state expression of CCND1 following either C134 (p = 0.0055) or C335 treatment (p = 0.0105)." (PMID 31340854, 2019). "ROS can stimulate the phosphorylation of MAPK and extracellular signal-regulated kinase (ERK), cyclin D1 expression and JUN N-terminal kinase (JNK) activation, all of which are linked to tumor cell survival and growth." (PMID 31921862, 2019). "CCND1 is a novel downstream target of miR‐551b‐3p and mediates the tumour suppressive role of miR‐551b‐3p." (PMID 31199052, 2019). "In summary, this study demonstrates that tumor markers Cyclin D1 and CD55 in A431 cells can be differentially modulated via activation of three ER subtypes, suggesting the involvement of ER signals in cancer cell progression." (PMID 31611744, 2019).
tumor (continued). "There was increased expression of pro-proliferative and tumor promoting genes such as Ccnb1, Ccnd1, Survivin, and Myc, while the expression of Cdkn1a, an inhibitor of cell cycle progression, was significantly reduced in Nlrp12-/- HCC." (PMID 30990169, 2019). "Our results show that tumor mutational burden, CIN markers, and co-occurring CCND1 and CDKN2A mutations are associated with chemoradiotherapy outcomes in advanced stage oro- and hypopharyngeal HNSCC patients, thereby highlighting their prognostic potential." (PMID 30934880, 2019). "Overexpression of cyclin D1, and cyclin E has been identified to provide proliferative advantage to the tumor cells." (PMID 31575007, 2019). "Taken together, these findings suggest that the high levels of proliferation seen in basal-like tumours are unlikely driven by traditional CCND1/RB1 signalling." (PMID 30819233, 2019). "The present study was conducted in human cSCC cell line to confirm the expression of all three ERs and to further investigate their activation by ER agonists on modulation of tumor markers Cyclin D1 and CD55." (PMID 31611744, 2019). "Such a finding suggeststhat cyclin D1 expression arises from the initial gastric lesions and tends toremain with tumor progression." (PMID 30624523, 2019). "The results indicated CCND1 plays an important role in the tumor progression in OSCC and is a prognostic marker." (PMID 31159251, 2019). "In lung cancer mouse models, blocking or deleting IL-6 reveals a delay in tumor progression and metastasis through deactivation of the IL-6/STAT3 pathway and cell proliferation regulator cyclin D1, as well as through enhancement of tumor cell apoptosis." (PMID 32039025, 2019). "On the other hand, the SR tumours from the mice treated with compound 9a showed significantly lower levels of cyclin D1 and three HCC biomarkers (α-fetoprotein, survivin and glypican 3) than those from the vehicle control-treated mice." (PMID 31754201, 2019). "The expression of CCND1 protein in xenograft tumour tissues from miR‐551‐3p group was significantly lower than that in control group (P < 0.05)." (PMID 31199052, 2019). "In particular, results from another large study—TransATAC (n = 1155)—are in line with our conclusions and show an increased risk of recurrence at 10 years in ER-positive endocrine-treated patients with CCND1-amplified tumours." (PMID 30819233, 2019). "Altogether, the results substantiate the role of the RN181–cyclin D1/CDK4 pathway in control of the tumour development of GC." (PMID 30714150, 2019). "Ectopic expression of GALR1 suppresses tumor cell proliferation through Erk1/2-mediated regulation of cyclin-dependent kinase inhibitors and cyclin D1." (PMID 31105737, 2019). "Functional analysis revealed that CCND1 regulates cell cycle progression and is actively involved in tumor cell carcinogenesis specific to cell and tissue type." (PMID 31205821, 2019). "YC-1 effectively suppresses tumor proliferation through repressing the transcription of Wnt-regulated genes such as cyclin D1." (PMID 31086087, 2019). "Consistent with our findings, a series of previous studies reveal that down‐regulation of Cyclin D1 or Cyclin B1 can be induced significantly less colony‐forming, stronger anti‐proliferative effect, and pro‐apoptosis ability in different tumor cell lines." (PMID 31173492, 2019). "Lastly, a study with an HCC rat model showed that probiotic fermented milk and chlorophyllin slow down tumor growth and volume for 40%, by reducing expressions of c-myc, bcl-2, cyclin D1, and rasp-21." (PMID 30658519, 2019). "Cyclin D1 nuclear staining was positive in 50% of neoplastic cells with weak to moderate intensity in the two subserosal tumors whereas the fundal tumor showed < 5% Cyclin D1 positive tumor cells." (PMID 31615558, 2019).
tumor (continued). "The anti-tumor effects of STAT3 decoy are associated with reduced tumor cell proliferation, induction of apoptosis, and reduced expression of STAT3 target genes, including the genes encoding Bcl-XL and cyclin D1." (PMID 31671769, 2019). "Then, Western blot was performed to confirm that Mfn2 was over expression in the tumor tissue of Adv-mfn2 group, and the expression of Cyclin D1 was decreased in Adv-control group." (PMID 31384172, 2019). "Our findings reveal that GR-selective liganding suppresses Y537S ER chromatin association at the CCND1 enhancer, inhibits mutant (Y537S) MCF-7 proliferation, and slows Y537S ER+ tumor growth." (PMID 31340854, 2019). "In this way, the reduction of Cyclin D1 mRNA and protein expression in hepatocarcinoma cells through AM-CM treatment, would probably reduce tumor growth." (PMID 31578445, 2019). "Further analysis showed that CCND1 mRNA level decreased with increasing ccRCC tumor grades and the rate of recurrence in ccRCC patients." (PMID 31183974, 2019). "Twenty-two percent (426/1965, 22%) and 35% (119/340, 35%) of tumours in cohorts 1 and 2, respectively, were found to harbour CCND1 amplifications, in line with previously published figures." (PMID 30819233, 2019). "CAGE displays tumor-promoting potential and promotes cell cycle progression by inducing expression of cyclin D1 and E in AP-1 and E2F-dependent manner." (PMID 31799196, 2019). "The superior anti-tumor activity of tubacin was linked to its ability to not only inhibit accumulation of mutant FGFR3, but also to cause robust downregulation of MYC and cyclin D1, and to induce a DNA damage response and apoptosis." (PMID 29423038, 2018). "We identified 18 FIBP-interacting proteins, among which GSK3β was selected for further study because it is widely recognized as a protein upstream of cyclin D1 and is closely related to tumor development." (PMID 30275459, 2018). "Cyclin D1’s function in facilitating the repair of potentially catastrophic DNA damage is supported by the finding that its depletion can sensitize tumor cells to ionizing radiation-driven cell death." (PMID 29423038, 2018). "Cyclin A2 expression was observed in 54 (83.1%) tumours, cyclin D1 in 58 (89.2%), cyclin B1 in 39 (60%), and cyclin E in 21 (32.8%)." (PMID 29785357, 2018). "Mice treated with ZnPP had a reduced xenograft growth and diminished cyclin D1 and Ki-67 staining in tumor sections." (PMID 30149527, 2018). "NPC tumors are characterized as tumors with relatively low single nucleotide mutation but with frequent hypermethylation, amplification of CCND1, deletion of tumor suppressor genes such as CDKN2A and 2B, and other chromosome abnormalities." (PMID 30236142, 2018). "Overexpression of SIRT1 was reported to inhibit cell proliferation and tumor development through the mechanism of downregulation of NF-kB activity and inhibition of cyclin D1 signaling." (PMID 29991742, 2018). "Among these genes, some target genes containing NF-κB binding sites in their promotors, such as COX-2, cyclin D1, and survivin, have been shown to contribute radioresistance in various types of tumor cells." (PMID 29743919, 2018). "The expressions of cyclin D1 and pRB were further confirmed by IHC staining of the xenograft tumor sections." (PMID 29789630, 2018). "Under growth-promoting conditions in EGF, FGF enriched serum-free medium, miR-449a suppresses Ccnd1 and inhibits migration and invasion, suggestive of a tumour-suppressive effect." (PMID 29720725, 2018). "Western blotting confirmed overexpression of ABHD11‐AS1 increased cyclin D1 expression in the xenograft tumours." (PMID 29799152, 2018).
tumor (continued). "Concurrently, the levels of G1/S transition‐associated proteins p21, cyclin D1 and CDK2 were also significantly decreased in tumour tissue compared with mice that received vehicle." (PMID 30247801, 2018). "The decrease in cyclin D1 and increase in histone H3 phosphorylated (p)-Ser10 were confirmed by immunohistochemistry in tumor tissues administered with zingerone." (PMID 30235818, 2018). "InS3-54 also inhibits STAT3 binding to cyclinD1 (CCND1) promoters in ChIP experiments and reduces tumor growth and metastasis." (PMID 29921764, 2018). "As CCND1 mRNA is expressed in the majority of MCL tumor cells, we explored the use of quantitative CCND1 mRNA from peripheral blood to monitor MRD." (PMID 29954415, 2018). "Overexpression of cyclin D1 was shown to correlate with early cancer onset and tumor progression, and can induce chemotherapeutic resistance and protection from apoptosis." (PMID 30235818, 2018). "Western blotting of the xenograft tumour tissues from the nude mouse model showed that overexpression of ABHD11‐AS1 increased the expression of cyclin D1, CDK1, CDK2, CDK4, Bcl‐xl and VEGFA and decreased the expression of p16." (PMID 29799152, 2018). "Cyclin D1 overexpression has been related with amplification of the CCND1 gene in several tumours including OSCC." (PMID 29785357, 2018). "In premenopausal patients randomized to tamoxifen versus control, the efficacy of tamoxifen was reduced in patients whose tumor carried CCND1 gene amplification as defined with FISH." (PMID 30041599, 2018). "Cyclin D1 is involved in early-onset tumor progression, and CCND1 represents the second most frequently amplified gene among all human cancer types." (PMID 30235818, 2018). "For p16, Cyclin D1 and Myc, a strong nuclear staining was observed in some tumor cells in all cases, which allowed for the easy calculation of positive cell percentage for each case." (PMID 29489901, 2018). "Cyclin D1 was present in almost 90% of the cases and highly expressed in 60% being the most detected cyclin in these tumours." (PMID 29785357, 2018). "Consistent with inhibition of the G0/G1-S transition, we also measured reduced expression of CDK4 in reprogrammed tumours and reduced RB phosphorylation at Ser780 (the RB amino acid substrate of the Cyclin D1-CDK complex) in reprogrammed tumours." (PMID 29662623, 2018). "In normal tissue, positivity of cyclin D1 was restricted to basal layers whereas in tumor samples positive nuclear staining was observed in all areas, with 80% of the cases showing >20–70% positive nuclear staining." (PMID 29464035, 2018). "Protein expression levels of CCND1 are related to the site of the tumor, depth of tumor invasion, and stage of the disease." (PMID 29443735, 2018). "The treatment of HTB-35 cells with Met caused the suppression of cyclin D1 gene (CCND1), which in most tumor cells is positively regulated by c-Myc." (PMID 29958416, 2018). "In this work, we have determined the biologic basis of CtBP2’s neoplastic activities in Apc-mutated neoplasia as linked to its regulation of TIC populations and transcriptional regulation of downstream Wnt targets, such as LGR5, c-Myc and cyclin D1." (PMID 30197752, 2018). "CCND1, also known as cyclin D1, is abnormally overexpressed in numerous cancers and promotes uncontrolled tumor growth through influencing cell-cycle progression." (PMID 30064475, 2018). "CCND1 region analysis revealed 26 (43.3%) tumours with the presence of numerical aberrations which were correlated with cyclin D1 high expression (Rho = 0.48; p < 0.001)." (PMID 29785357, 2018). "Many studies focusing on the oncogenic functions of c-Fos have demonstrated its involvement in tumor growth through the modulation of Cyclin D1, which is a nuclear regulatory subunit of the cyclin-dependent kinases (CDK)-4 and CDK-6." (PMID 30423928, 2018).